U2 (U2 spliceosomal RNA )
Synonyms: LOC124904145
Gene: Small nuclear RNA gene on chromosome 17 (43,290,291 to 43,290,481, reverse strand). Ensembl gene ENSG00000274452.
Gene Ontology:
Molecular function: pre-mRNA branch point binding
Biological process: mRNA branch site recognition
Cellular component: U2 snRNP
Homologues: Orthologues: pig U2 (98% identical), guinea pig U2 (98% identical), mouse Gm26316 (97% identical), dog U2 (97% identical), rabbit U2 (96% identical), rat U2 (96% identical), rat LOC120102750 (95% identical), pig U2 (83% identical), tropical clawed frog U2 (40% identical). Paralogues in human: U2 (95% identical), RNU2-2 (93% identical), RNU2-6P (93% identical), RNU2-4P (91% identical), RNU2-26P (90% identical), RNU2-57P (90% identical), RNU2-3P (88% identical), RNU2-59P (88% identical), RNU2-64P (87% identical), RNU2-68P (87% identical), RNU2-48P (86% identical), RNU2-70P (86% identical), and 66 more.